USH1G (USH1 protein network component sans)
Description:
Plays a role in pre-mRNA splicing by regulating the release and transfer of U4/U6.U5 tri-small nuclear ribonucleoprotein (tri-snRNP) complexes from their assembly site in Cajal bodies to nuclear speckles, thereby contributing to the assembly of the pre-catalytic spliceosome on target pre-mRNAs. May also participate in recycling of snRNPs back to Cajal bodies during splicing. Plays a role in regulating MAGI2-mediated endocytosis. Anchoring/scaffolding protein that is a part of the functional network formed by USH1C, USH1G, CDH23 and MYO7A that mediates mechanotransduction in cochlear hair cells. Required for normal development and maintenance of cochlear hair cell bundles. Required for normal hearing.
Synonyms: SANS; FLJ33924; ANKS4A
Tractability: Antibody: UniProt places it where antibodies can reach, with high confidence; its Gene Ontology location is reachable by antibodies, with medium confidence.
Gene: Protein-coding gene on chromosome 17 (74,916,083 to 74,923,256, reverse strand). Ensembl gene ENSG00000182040.
Subcellular location: Cytoplasm, cytosol; Cytoplasm, cytoskeleton; Cell membrane; Cell projection, cilium; Nucleus speckle; Nucleus, Cajal body; Cytoplasm, cytoskeleton, microtubule organizing center, centrosome; Photoreceptor inner segment
Subcellular location (Human Protein Atlas): Vesicles; Cytosol; Nucleoplasm
Pathways (Reactome):
Sensory Perception: Sensory processing of sound by inner hair cells of the cochlea; Sensory processing of sound by outer hair cells of the cochlea
Gene Ontology:
Molecular function: identical protein binding; protein binding; spectrin binding
Biological process: equilibrioception; photoreceptor cell maintenance; regulation of clathrin-dependent endocytosis; sensory perception of light stimulus; sensory perception of sound
Cellular component: Cajal body; ciliary base; cytosol; nuclear speck; photoreceptor cell cilium; photoreceptor inner segment; actin cytoskeleton; plasma membrane; centrosome; ciliary basal body; cilium; cytoplasm; cytoskeleton; photoreceptor connecting cilium; plasma membrane bounded cell projection
Genetic constraint (gnomAD): Loss-of-function variants: 27 observed, 30.91 expected, observed/expected ratio (o/e) 0.87, 90% interval 0.64 to 1.21. The upper end of that interval is the gene's LOEUF score, 1.21, which puts it in group 5 of 6, group 1 being the genes least tolerant of losing a copy. Missense variants: 674 observed, 642.41 expected, observed/expected ratio (o/e) 1.05, 90% interval 0.98 to 1.12. Synonymous variants: 266 observed, 274.38 expected, observed/expected ratio (o/e) 0.97, 90% interval 0.88 to 1.07.
Gene-disease validity (ClinGen):
ClinGen rates the evidence that USH1G causes each of these diseases.
Usher syndrome type 1 (autosomal recessive): Definitive. A syndrome characterized by congenital, bilateral, severe sensorineural hearing loss, abnormalities in the vestibular system, and adolescent-onset retinitis pigmentosa.
nonsyndromic genetic hearing loss (autosomal recessive): Disputed. A disease characterized by hearing loss that is not part of a larger syndrome.
Homologues: Orthologues: chimpanzee USH1G (99% identical), macaque USH1G (99% identical), guinea pig USH1G (97% identical), mouse Ush1g (96% identical), pig USH1G (96% identical), rat Ush1g (96% identical), dog USH1G (95% identical), tropical clawed frog ush1g (71% identical), zebrafish ush1ga (70% identical), zebrafish ush1gb (64% identical), Drosophila melanogaster Sans (36% identical). Paralogues in human: ANKS4B (41% identical).
Diseases named in the same sentence as USH1G in open-access papers:
USH1G is named in the same sentence as 19 diseases in open-access papers, as found by Europe PMC text mining. Sharing a sentence is not in itself a finding about the gene and the disease. The quoted sentences say what the papers report.
Usher syndrome (31 papers, 2011 to 2025). A syndromic diseae characterized by the association of sensorineural deafness (usually congenital) with retinitis pigmentosa and progressive vision loss. "It is classified into three clinical types and twelve genetic subtypes.We report a case of a family affected by Usher syndrome due to a variant in the USH1G gene, coding for the SANS protein." (PMID 41060164, 2025). "Molecular analysis identified the homozygous p.Glu171Ter variant in the USH1G gene.We highlight the importance of an early diagnosis of Usher syndrome." (PMID 41060164, 2025). "Pathogenic variants of USH1G lead to the human Usher syndrome (USH), the most common form of combined hereditary deaf-blindness in humans." (PMID 39594604, 2024). "One functional study has demonstrated that mutations in MYO7A weakens its ability to form MYO7A/USH1C/USH1G complex which impairs phase separation, resulting in an abnormal tip-link densities and causing hearing and vision loss in Usher syndrome patients." (PMID 37985665, 2023). "The ciliopathy protein SANS/USH1G, mutations of which lead to Usher syndrome, was shown to regulate pre mRNA splicing and interact with splicing factors SON and SF3B1." (PMID 35295905, 2022). "USH1G is responsible for Usher syndrome type 1, an autosomal recessive condition that associates a congenital, profound SN HL, vestibular areflexia, and adolescent-onset retinitis pigmentosa." (PMID 34440452, 2021). "Mutations in SANS cause Usher syndrome type 1G (Ush1g) characterized by congenital profound sensorineural hearing loss and vestibular dysfunction at birth with onset of retinitis pigmentosa by adolescence." (PMID 30210291, 2018). "The “rarest” Usher syndrome genes with mutations were as follows: USH1G (1 patient), CLRN1 (1 patient), PCDH15 (2 patients), and USH1C (4x)." (PMID 28944237, 2017). "Since the discovery of USH1G as causally linked to the most severe form of Usher syndrome (type I-), several pathogenic variants of this gene in affected families have been identified, among which are eight nonsense mutations like the c.1162G>T variant reported here." (PMID 37893031, 2023). "USH1G/SANS deficiency altered the kinetics of spliceosome activation leading to perturbations in constitutive and alternative splicing of target genes, especially genes related to the human Usher syndrome." (PMID 38139438, 2023). "USH1G encodes the protein SANS and is responsible for Usher syndrome Type 1G (MIM 606943)." (PMID 26561413, 2015). "Notably, two novel mutations of USH1G were recently reported in individuals with atypical Usher syndrome (p.D458V and c.163_164+13del15)." (PMID 22219650, 2011). "During this process, SANS interacts with the U4/U6 and U5 snRNP-specific proteins PRPF31 and PRPF6 and regulates splicing, which is disturbed by variants of USH1G/SANS causative for human Usher syndrome (USH), the most common form of hereditary deaf–blindness." (PMID 38139438, 2023). "Our investigation revealed in both the proband and her sister a very rare truncating variant in USH1G and a previously undescribed missense substitution in ADGRV1, two genes linked to type I (OMIM 606943) and type II (OMIM 605472) Usher syndrome, respectively." (PMID 37893031, 2023). "Both USH1G and ADGRV1 are linked to Usher Syndrome (annotated as # 606943 and # 605472, respectively, in the OMIM database), a rare autosomal recessive disorder characterized by profound congenital hearing impairment and subsequent retinitis pigmentosa." (PMID 37893031, 2023). "Five genes (USH2A, USH1G, USH1C, MYO7A, and PCDH15) were associated with Usher syndrome from Africa." (PMID 34609590, 2022). "Variants from three known Usher syndrome genes USH2A, USH1G, and USH1C were found from the records retrieved." (PMID 34609590, 2022). "Three patients had hearing loss and were diagnosed with Usher syndrome, and they independently carried CDH23, PCDH15, and USH1G variants." (PMID 34721897, 2021).
Usher syndrome (continued). "Currently, up to 13 genes have been associated with Usher syndrome: MYO7A, USH1C, CDH23, PCDH15, USH1G, and CIB2 are responsible for USH1, although the role of CIB2 in the Usher syndrome has recently been put on doubt." (PMID 31231422, 2019). "Genomic DNA sequencing revealed that the siblings shared two monoallelic variants in two genes linked to Usher Syndrome (USH genes), a recessive disorder of the ear and the retina: a rare pathogenic truncating variant in USH1G and a previously unreported missense variant in ADGRV1." (PMID 37893031, 2023). "Usher syndrome is heterogenous, both in terms of clinical presentation and genetic origin, with a number of diverse genes known to carry pathogenic mutations (Type 1: MYO7A, USH1C, PCDH15, CDH23, USH1G, and CIB2; Type 2: USH2A, ADGRV1, and WHRN; Type 3: CLRN1)." (PMID 38474133, 2024). "Notably, Müller glial cells also expressed the other USH1-associated genes USH1G, USH1C, CDH23, and CIB2, suggesting that Müller glial cells may be more mechanistically relevant to Usher syndrome pathology than previously considered." (PMID 38474133, 2024). "Mutations in SANS cause Usher syndrome type 1G (USH1G), which accounts for approximately 1% of USH cases." (PMID 33193648, 2020). "GRXCR1 is an enzyme that has been shown to remove glutathione groups from target proteins, and it has been suggested to destabilize the interaction between the Usher Syndrome proteins USH1C and USH1G in zebrafish." (PMID 35235570, 2022). "USH1G interacts with USH1C, a known gene involved in Usher syndrome." (PMID 30828346, 2019). "USH1G has been observed to have a minor role in Usher syndrome in Spanish population, but not in MD, even though they share similar hearing loss profile." (PMID 30828346, 2019).
deafness (9 papers, 2011 to 2024). An inherited or acquired condition characterized by the complete loss of the ability to hear from one or both ears. "Remarkably, bilateral gene therapy carried out as late as P30 led to significant utricular recovery in Ush1g–/– mice, suggesting that the time window for gene therapy is broader for vestibular deficits linked to USH1G than for the associated deafness." (PMID 38194286, 2024). "In the inner ear, USH1G-associated deafness is more likely caused by defects in the assembly of mechanosensitive tip-link complex in the stereocilia of auditory hair cells." (PMID 39594604, 2024). "In addition, a region on chromosome 17 also identified in ITU cluster A contains seven genes that include USH1G, mutations in which cause autosomal recessive deafness in both humans and mice." (PMID 29191164, 2017). "We also extended our evolutionary studies to the Ush1g deafness gene because of the tight head-to-tail physical clustering of Ush1g with Otop2 and Otop3 in vertebrate genomes, and because mutations in Otop1 and Ush1g result in inner ear phenotypes in vertebrates." (PMID 21261979, 2011). "In the two simplex families, compound heterozygous variants c.5426+1G > A and c.6087-3T > G in PTPRQ were identified in the proband of Family E and homozygous variant c.164+5G > A in USH1G in Family F. No other candidate variants in known deafness genes have been identified." (PMID 34956325, 2021). "Ush1g knockout mice, which lacked Sans, displayed no ABR to sound, indicating complete deafness, as well as severe vestibular dysfunction." (PMID 38137568, 2023).
hearing loss (8 papers, 2018 to 2023). "A fourth rare variant, c.379A>G (p.(Ser127Gly)), was found within OTOP2, a gene which maps to the candidate region of Usher syndrome 1G (USH1G), which includes congenital hearing loss, vestibular areflexia, and adolescent-onset retinitis pigmentosa." (PMID 37107589, 2023). "Several variants of the USH1 genes, MYO7A, CDH23, and USH1G, sometimes with digenic inheritance, have been reported to be linked to atypical USH with variable age at onset and severity of the hearing loss and RP." (PMID 35353227, 2022). "Recent study suggests that an enrichment of rare variants in hearing loss genes such as GJB2, SLC26A, or USH1G may contribute to explain these phenotypic heterogeneities." (PMID 32038468, 2019). "Mutations of MYO7A, CDH23, USH1C, PCDH15, USH1G, and WHRN can cause non-syndromic recessive hearing impairment, and MYO7A variants are also associated with a non-syndromic dominant form of hearing impairment." (PMID 35353227, 2022).
retinal degeneration (2 papers, 2010 to 2018). Degeneration of the retina. "These genes include those that encode proteins associated with Usher (USH1G, USH2A) and Bardet-Biedl syndromes (BBS10); both are genetic human diseases of the cilia with wide ranging symptoms including retinal degeneration." (PMID 20939902, 2010). "This absence of morphological or functional abnormalities in Ush1g−/− and Ush1c−/− C57Bl/6 J mice was consistent with the lack of retinal degeneration observed in previously reported harmonin mouse models." (PMID 29386551, 2018).
adenoma (1 paper, 2013). A neoplasm arising from the epithelium. "The villus, crypt and ISC preparations were subjected to bisulfite pyrosequencing of eleven specific DMRs, among them Dusp6 and Fos (containing adenoma-hypomethylated DMRs), as well as Ush1g and Vdr (containing adenoma-hypermethylated DMRs)." (PMID 23408899, 2013).
cardiomyopathy (1 paper, 2020). A disease of the heart muscle or myocardium proper. "For example, mutational combination of PCDH15 and USH1G have been identified in non‐syndromic hearing loss; oligogenic inheritance of three cardiomyopathy‐associated genes has been reported in a family with cardiac anomaly and supported by experimental evidence." (PMID 32815649, 2020).
Nystagmus (1 paper, 2024). Rhythmic, involuntary oscillations of one or both eyes related to abnormality in fixation, conjugate gaze, or vestibular mechanisms. "However, most (8 of 9) of the treated Ush1g–/– mice had unilateral spontaneous nystagmus, suggesting that the restoration of vestibular function was likely asymmetric in most individuals." (PMID 38194286, 2024).
infection (1 paper, 2024). The state of being infected such as from the introduction of a foreign agent such as serum, vaccine, antigenic substance or organism. "Similarly, the promoter region of OTOP2 and USH1G (nearby genes on sense and antisense strands) with increased accessibility (infection-biased OCRs) had concurrently modest increased gene expression." (PMID 38862613, 2024).
retinopathy (1 paper, 2025). "This variant is unlikely to be contributing to the retinopathy observed in this individual because USH1G is associated with a different condition, characterized by congenital profound hearing loss and early-onset RP." (PMID 40081374, 2025).
tumor (1 paper, 2024). "Age, N stage, and pTNM stage were identified as risk factors, whereas tumor grade, and B3GNT3, MACC1, NELL2, and USH1G were identified as protective variables." (PMID 38818465, 2024).
USH1G also shares sentences with these, for which no sentence is quoted: Usher syndrome type 1 (6 papers); retinitis pigmentosa (4); Hearing impairment (2); Ataxia (1); autosomal recessive deafness (1); Bardet-Biedl syndrome (1); genetic disorders (1); glioma (1); schizophrenia (1).